INS (insulin)
Diseases named in the same sentence as INS in open-access papers (continued):
Sharing a sentence is not in itself a finding about the gene and the disease.
amyloidosis (115 papers, 2009 to 2026). A disorder characterized by the localized or diffuse accumulation of amyloid protein in various anatomic sites. "The biopsy sample resulted in amyloid protein identification by mass spectrometry showing amyloidosis, insulin-type (AIns), consistent with iatrogenic localized amyloidosis associated with insulin injection areas in diabetic patients." (PMID 39081432, 2024). "Insulin, a small polypeptide hormone, is associated with injection-site amyloidosis and is a popular model protein for in vitro studies of amyloid aggregation processes as well as in the search for potential anti-amyloid compounds." (PMID 39273350, 2024). "In this study, we have addressed the questions on the chronological changes, causal relationships, and the molecular mechanisms of insulin resistance and amyloid pathology in a mouse model of AD with metabolic and genetic interventions." (PMID 30975165, 2019). "Our previous studies showed that insulin-derived amyloidosis causes poor glycemic control and increased insulin dose requirements because of impairments in insulin absorption." (PMID 31196059, 2019). "Multiple daily subcutaneous injections (MDSIs) are mainly used for formulating an insulin therapy for diabetic patients; however, they also cause insulin-derived amyloidosis (IDA) and lead to poor glycemic control." (PMID 31687164, 2019). "The amyloid plaques have been implicated in the destruction of pancreatic β-cells that synthesize both amylin and insulin." (PMID 23457571, 2013). "The amyloid plaques have been implicated in the destruction of pancreatic β-cells, which synthesize amylin and insulin." (PMID 23457571, 2013). "It is known that in 20% acetic acid at ambient temperatures insulin is preferentially in the monomeric form, most susceptible to subsequent amyloidosis upon quenching to elevated temperature." (PMID 22848214, 2012). "Insulin amyloid-like fibrils are the hallmark of a clinical condition observed in insulin-dependent diabetic patients, called insulin injection amyloidosis." (PMID 21819598, 2011). "In addition, the number of works aimed at the study of the local iatrogenic amyloidosis caused by insulin aggregation is increasing." (PMID 37629113, 2023). "This suggests that while advanced amyloid pathology (ApoE ε4 positive) may be associated with reduced central insulin activity, older individuals with less pronounced neuropathological changes may still respond to elevated levels of the ligand." (PMID 36009470, 2022). "We evaluated the inhibitory effect of NQTrp and Cl-NQTrp toward aggregation of Calcitonin, Insulin and Lysozyme aggregation, which form amyloids in vivo and are implicated in medullar carcinoma of the thyroid, insulin injection amyloidosis and hereditary systemic amyloidosis, respectively." (PMID 31750300, 2019). "In fact, insulin has been shown to aggregate forming amyloid fibrils in the site of medication injections of diabetic patients causing a pathological condition, named insulin injection amyloidosis." (PMID 29182566, 2017). "Another use for the method established in the current study may be to investigate the tendency of various insulin types to cause amyloidosis." (PMID 25009591, 2014). "A previous study demonstrated that insulin injections are associated with local amyloidosis." (PMID 25009591, 2014). "Insulin is a nearly all-alpha protein playing a central role in blood glucose homeostasis and is associated with a medical condition termed insulin injection amyloidosis, characterized by the formation and deposition of amyloid fibrils from insulin." (PMID 21819598, 2011). "Although the mechanism of GSK3 modulation in the AD brain is far from completely understood, it is reasonable to speculate that the regulation of insulin deficiency in APP processing to the amyloidosis pathway is, at least partly, through activation of GSK3 signaling." (PMID 21044348, 2010).
amyloidosis (continued). "Insulin is known to form subvisible particles and amyloid material, which can lead to iatrogenic amyloidosis and reduced potency necessary for glycemic control." (PMID 41867589, 2026). "Pathologically, at frequent insulin injection sites, insulin can aggregate into amyloid fibrils, leading to localized amyloidosis, where the fibrils arestabilized by hydrophobic interactions and disulfide bonds, forming the amyloid core." (PMID 41409210, 2025). "Since then, there have been more than 75 similar cases in patients using a wide variety of insulin formulations, suggesting that the incidence of insulin-derived amyloidosis is increasing." (PMID 39081432, 2024). "The onset of insulin-derived amyloidosis ranges from several years to decades, with development affected by factors such as insulin dosing, injection technique, absorption, and clearance." (PMID 39081432, 2024). "In this regard, compared to the amyloid group, rats that underwent treadmill exercise for 4 weeks in addition to intranasal insulin pretreatment and therapy showed higher levels of IGF1, BDNF, and GLUT4 gene expression in the hypothalamus." (PMID 38987609, 2024). "To further explore the potency of curcumin or its complex V-Cur to affect the formation of amyloid-like aggregates, we investigated their effect on insulin fibrillation, a common approach for simulating amyloidosis events." (PMID 39796150, 2024). "This basic research work can pave the way to further investigations concerning insulin amyloidosis, suggesting the use of saponins as amyloid inhibitors and/or stabilizing agents in solution." (PMID 39858435, 2024). "In light of the recent findings on the insulin fibrils structure and on insulin-derived amyloidosis, it appears important to look for the potential inhibitors of its aggregation." (PMID 39858435, 2024). "At low insulin concentrations, the insulin-degrading enzyme hydrolyzes β-amyloid peptides with high efficiency, thereby preventing the formation of β-amyloid plaques and the AD development." (PMID 36834685, 2023). "An example is recombinantinsulin, in which long-term subcutaneous administration can resultin the development of localized insulin-derived amyloidosis at theinjection sites." (PMID 38031413, 2023). "The number of fibril aggregates per unit area was also higher in the insulin group, and it seemed that with this rise, the context became more suitable for the development of insulin-amyloid plaques." (PMID 36856252, 2023). "In diabetic patients, injection amyloidosis can occur due to accumulation of the insulin that they use as treatment." (PMID 35563343, 2022). "In insulin-derived amyloidosis, for example, repeated injection of insulin subcutaneously in the same spot leads to the creation of insulin amyloid lumps in some diabetic patients." (PMID 35453734, 2022). "Accordingly, inhibition of neddylation preserved synaptic insulin signaling and rescued memory deficits in mice with a high amyloid load, which were fed with a 'western diet'." (PMID 34986876, 2022). "Nevertheless, previous studies have shown a relationship between insulin resistance and amyloid genesis in AD." (PMID 35215222, 2022). "After 21 consecutive days of subcutaneous injection of human insulin amyloid fibrils, local amyloidosis in mice was generated, and within the tumor, lipohypertrophy, which includes the amyloid fibrils, was present." (PMID 35563343, 2022). "In the present study, the generation of local amyloidosis in rats has been studied in more detail (injection of insulin or fibril, duration of injection, testing animal’s serum...)." (PMID 35563343, 2022). "This suggests that GLP-1R agonists forestall neuroinflammation by preventing insulin resistance and the mutually exacerbated amyloid pathology." (PMID 36117625, 2022). "Insulin-derived amyloidosis manifests itself by the presence of a hard subcutaneous mass at the injection site." (PMID 35563343, 2022).
amyloidosis (continued). "The main purpose of this study was the induction of localized insulin-generated amyloidosis and the observation of silymarin effects on this process." (PMID 35563343, 2022). "The only pancreatic tumor associated with amyloidosis is Insulin expressing pancreatic neuroendocrine tumor, which is rarely associated with IAPP-type amyloidosis." (PMID 33579198, 2021). "Insulin amyloid-like fibrils are the hallmark of a clinical condition observed in insulin-dependent diabetic patients, called insulin injection amyloidosis in which insulin fibrils are found at the site of insulin injections." (PMID 34205510, 2021). "Of note, when α-value was updated with additional amyloid proteins, such as lysozyme, insulin and semenogelin, the identification of amyloidosis subtyping resulted in agreement with NAC findings." (PMID 33805439, 2021). "By an in‐depth and comprehensive platelet proteomic analysis in T2DM‐MCI vs T2DM‐nMCI patients, we demonstrated that the differentially expressed proteins were mainly enriched in amyloidosis, mitophagy/autophagy and insulin signaling pathways." (PMID 34528736, 2021). "It is therefore important to understand the fibrillation of this protein, both to increase our understanding of insulin-related amyloidosis, and to improve on existing industrial production procedures." (PMID 31901953, 2020). "Insulin-derived amyloidosis (insulin ball) is an iatrogenic complication of diabetic patients treated with insulin drugs." (PMID 35515176, 2020). "Specifically, insulin-derived amyloidosis (IDA) is a pathological complication of insulin therapy in which amyloid deposits are formed in the insulin injection site triggering an inflammatory response and necrosis in the surrounding tissue." (PMID 32629793, 2020). "It turns out that another substrate for neprilysins (next to glucagon, insulin, substance P and many others) is amyloid, thus, lowering its level promotes the formation of its deposits and the formation of amyloid plaques." (PMID 32366041, 2020). "Insulin injection can also lead to several types of localized lesions, including lipoatrophy, cutaneous lipohypertrophy, allergic reaction, and insulin-derived amyloidosis." (PMID 33167495, 2020). "Insulin fibrillation can cause significant complications in diabetes therapy, either directly due to injection site amyloidosis, or indirectly by decreasing the long-term stability of insulin formulations." (PMID 31901953, 2020). "In this report, a case of toxic insulin-derived amyloidosis in which the effect of toxicity on the surrounding tissue was examined is presented." (PMID 31196059, 2019). "LC/MS of the fat aspirate revealed AIns, a form of iatrogenic amyloidosis related to insulin administration that is typically localized and benign." (PMID 30837451, 2019). "The area of insulin-derived amyloidosis that corresponded to the Congo red-positive portion on each specimen was microdissected." (PMID 31196059, 2019). "All biopsied masses corresponded histologically to the amorphous deposits that were positive for apple-green birefringence by Congo red staining and for insulin by immunostaining, confirming that the masses were insulin-derived amyloidosis." (PMID 31196059, 2019). "Insulin-derived amyloidosis is a skin-related complication of insulin therapy that interferes with insulin therapy." (PMID 31196059, 2019). "Although toxicities of in vitro-formed insulin amyloid fibrils have been well studied, the toxicity of insulin-derived amyloidosis remains to be clarified." (PMID 31196059, 2019). "This case highlights that ultrasonography, which is a noninvasive imaging modality, can be useful for detection of insulin-derived amyloidosis." (PMID 29403667, 2017). "After evaluation using ultrasonography and computed tomography, a total mass excision was performed, and a diagnosis of insulin-derived amyloidosis was made." (PMID 29403667, 2017).
amyloidosis (continued). "Amyloid fibrils form from spontaneously misfolded amylin, depositing in islet cells to elicit apoptosis, beta cell degeneration and decrease insulin secretion, with amyloidosis affecting up to 80% of pancreatic islet cells in T2D." (PMID 28754022, 2017). "We found that intranasal insulin treatment improved cognitive deficits and insulin signaling, reduced Aβ production and amyloid plaque burden, and increased neurogenesis in young APP/PS1 mice." (PMID 27457264, 2016). "Because high level peripheral insulin secretion impairs amyloid clearance by inhibiting brain insulin production which is a beneficial effect on amyloid clearance." (PMID 27273250, 2016). "Fibrillation of insulin reduces its effectiveness and is responsible for injection amyloidosis, observed in insulin dependent diabetic patients who receive insulin frequently." (PMID 27870861, 2016). "One example of when local amyloidosis occurs is following repeated insulin injections in diabetic patients." (PMID 25009591, 2014). "Insulin is a hormone that regulates blood glucose homeostasis and is a central protein in a medical condition termed insulin injection amyloidosis." (PMID 21819598, 2011). "With the expanding volume of literature on the topic, insulin-derived amyloidosis should now be considered a differential diagnosis for masses of unknown etiology in diabetic patients." (PMID 39081432, 2024). "In addition, curcumin and V-Cur were able to impede amyloidosis, as determined by the insulin fibrilization assay, but V-Cur appears to be more effective than curcumin, as significantly lower doses of V-Cur than curcumin were required to mediate this effect." (PMID 39796150, 2024). "Serum insulin levels were found to be lower at amyloidosis sites." (PMID 39081432, 2024). "There is a clinical overlap between insulin-derived amyloidosis and lipohypertrophy, which may lead to misdiagnosis." (PMID 39081432, 2024). "This improvement is possibly attributed to metformin’s capacity to stimulate adult hippocampal neurogenesis, deter amyloid plaque formation, restore normal insulin signaling within neural cells, and ameliorate pathological alterations in neural lines subjected to chronic high-insulin conditions." (PMID 39220736, 2024). "Peptide-based inhibitors have great potential and they could be a good choice to improve the quality of life of people suffering from insulin-derived amyloidoses." (PMID 36674821, 2023). "Several downstream signaling molecules activated by insulin are located in the brain, and it has been suggested that insulin may play a role also in other types of amyloidoses." (PMID 36674821, 2023). "Subcutaneous insulin injection may cause several types of injection site-related lesions, such as lipohypertrophy, lipoatrophy, and insulin-derived amyloidosis." (PMID 36674821, 2023). "Interestingly, not only insulin significantly contributes to the formation of amyloid plaques but also amylin co-secreted with insulin favors this process." (PMID 36923118, 2023). "We suggest that this and similar studies may develop a proposal on various compounds that could be used to counteract the underestimated problem of insulin-generated amyloidosis." (PMID 35563343, 2022). "Thus far, we are not aware of other studies investigating inflammation-related parameters in subcutaneous insulin-derived amyloidosis." (PMID 35563343, 2022). "In conclusion, we believe that silymarin could be effective in counteracting insulin-generated local amyloidosis." (PMID 35563343, 2022). "In addition, their accumulation in the body of patients leads to the development of a hereditary systemic lysozyme amyloidosis and insulin-derived amyloidosis." (PMID 32008441, 2020).
amyloidosis (continued). "Peptide aggregates have also been associated with a number of disease states; for instance, insulin aggregation, and the subsequent formation of amyloid fibrils, is known to result in insulin injection amyloidosis and injection site immune reactions as well as poor glycaemic control in many cases." (PMID 33096803, 2020). "Indeed, insulin-derived amyloidosis can occur in adipose tissue at sites of repeated insulin administration (insulin injection amyloidosis, iatrogenic insulin-amyloid type, injected-localised insulin amyloid, insulin balls, amyloidoma)." (PMID 33353193, 2020). "Insulin-derived amyloidosis is a skin-related complication of insulin therapy." (PMID 31196059, 2019). "Thus, the amyloid accumulation in the NASH induced group is enhanced by limiting Aβ degradation via decreasing the insulin sensitivity which in turn competes for the IDE sites and impairs aggregated amyloids clearance." (PMID 26576191, 2015). "From 1983, incidences of amyloidosis in insulin injection sites have been reported in rats." (PMID 25009591, 2014). "The exact mechanism by which insulin-induced amyloidosis occurs remains largely unknown in the scientific literature." (PMID 25009591, 2014). "Additionally, it has the ability to aggregate and form amyloid-like fibrils that are characteristic of a clinical condition called insulin injection amyloidosis." (PMID 21819598, 2011). "Research has shown that insulin degrading enzyme can break down amyloid beta (Aβ), indicating that insulin resistance could potentially contribute to changes in Aβ metabolism and increased amyloid pathology in AD." (PMID 39477682, 2025). "Moreover, PFT hindered amyloid plaque accumulation via the enhancement of insulin-degrading enzyme." (PMID 34306309, 2021). "However, the toxicity of insulin-derived amyloidosis itself remains to be clarified." (PMID 31196059, 2019). "Thus, the existence of insulin-derived amyloidosis interferes with insulin therapy." (PMID 31196059, 2019). "Thus, localized amyloidosis was obtained by the subcutaneous injection of insulin fibrils." (PMID 25009591, 2014). "Furthermore, AD-associated neuropathologies—including extracellular amyloid-β (Aβ) plaques—may exacerbate cerebral insulin resistance, suggesting the presence of a bidirectional feedback loop in which amyloid accumulation and insulin signaling deficits reinforce one another." (PMID 40507832, 2025). "Phosphorylation of tau protein by GSK-3β and the protective effect of insulin are well established, while involvement of GSK-3α in amyloid plaque formation is also suggested; thus, its inhibition is clearly connected to the anti-AD effect." (PMID 41226821, 2025). "Insulin gene knockout mice were found to show an increase in GSK-3β activity and tau hyperphosphorylation, with excessive deposition of amyloid plaques in hippocampal neurons." (PMID 38536493, 2024). "A speculative interpretation of these relationships is that insulin treatment enhanced the immune/inflammatory response which in turn improved microglial phagocytosis and degradation of amyloid, preventing increased CSF concentrations, and amyloid-induced elevations in P-tau." (PMID 35079029, 2022). "Moreover, the structural similarity of these proteins with human insulin and human lysozyme, which are associated with the injection-localized amyloidosis, and hereditary non-neuropathic systemic amyloidosis, respectively, make them ideal model structures for amyloid-related studies." (PMID 33362209, 2020). "Next, we verified whether insulin fibrils formed at neutral and acidic pH showed the typical intrinsic blue-green fluorescence, which has been described to be concomitant with the appearance of fibrillar structure in several proteins related to amyloid diseases." (PMID 29182566, 2017). "Again, IAPP inhibition is also proposed via an indirect mechanism, whereby a reduction in an individual’s insulin requirements will in turn reduce the production of IAPP and therefore amyloidosis." (PMID 28754022, 2017).